SNORA59A (small nucleolar RNA, H/ACA box 59A)
Synonyms: ACA59
Gene: Small nucleolar RNA gene on chromosome 1 (12,507,246 to 12,507,397, forward strand). Ensembl gene ENSG00000239149.
Gene Ontology:
Biological process: RNA processing
Cellular component: nucleolus
Homologues: Orthologues: chimpanzee SNORA59A (100% identical), macaque SNORA59A (91% identical), pig SNORA59A (61% identical).